MMP3 (matrix metallopeptidase 3)
Diseases named in the same sentence as MMP3 in open-access papers (continued):
Sharing a sentence is not in itself a finding about the gene and the disease.
cancer (continued). "Large variations in serum MMP-3 levels observed in the cancer patient group in the present study are attributable to the increased number of malignant epithelial cells, which potentially compromised the decreased expression of MMP-3 in CAFs at different levels." (PMID 28831065, 2017). "Since several substrates of matriptase, such as urokinase (uPA), stromelysin (MMP3), pro-HGF (hepatocyte growth factor), and PAR2 (protease-activated receptor 2), were implicated in cancer progression, the role of matriptase in cancers has been intensely addressed recently." (PMID 29118397, 2017). "Increased MMP3 activities may contribute to cancer progression." (PMID 29285307, 2017). "Such factors, which include the collagenases MMP-1 and MMP-13 and the stromelysin MMP-3, have well documented roles in disease progression and can in particular aid cell penetration through extracellular matrices, supporting invasion and metastasis in several cancer types." (PMID 25596732, 2015). "To further generalize our findings, we used LPS to stimulate murine macrophages (RAW264.7) to imitate inflammation and measured Mmp3, Mmp10, and Mmp13 expression over time; the mRNA levels were significantly increased, indicating that these three genes are upregulated in inflammation-cancer link." (PMID 25742789, 2015). "Among these, MMP3 has been demonstrated to facilitate EMT, increase cell motility, and promote metastatic spread in a variety of cancers." (PMID 41583390, 2026). "Among the 22 investigated MMPs, seven genes (MMP2, MMP3, MMP10, MMP12, MMP14, MMP15, and MMP16) were upregulated in cancer, while MMP8 was downregulated." (PMID 41728806, 2026). "MMPs of the matrilysin (MMP-7 and MMP-26) and stromelysin (MMP-3 and MMP-10) groups also play an essential role in cancer pathogenesis." (PMID 40332487, 2025). "The interaction between MMP3 and HSPA9 can impact cancer therapy by influencing ER-mitochondrial calcium flux, cell fate under stress, and mitochondrial function." (PMID 40362252, 2025). "KITENIN expression is associated with MAPK signaling and the AP-1 axis, and knockdown of KITENIN downregulates markers of cyclin D1, COX2, MMP3 and ERK1/2, HIF-1A, EMT, stemness and aerobic glycolysis, suppressing cancer progression." (PMID 39030594, 2024). "MMP3 is highly expressed in the CRC tissues and is indicated to promote cancer cell migration and invasion." (PMID 38166604, 2024). "The possible molecular mechanism involved in cancer pathways, PI3K-Akt signaling pathway and viral carcinogenesis pathway via the inhibition of CASP3, MMP3, SRC, MAPK10 and CDK6 and the activation of PPARα and JAK." (PMID 38675723, 2024). "To validate our findings, we recruited a cohort of 21 cancer patients for histological confirmation, revealing significant mRNA upregulation of STAT3, IL6, MMP9, MMP3, TGFB1, VEGF and HIF1A, coupled with downregulation of LHPP and PCK1, PTEN and BLC2." (PMID 39468431, 2024). "CEBPD has been identified as a regulator of MMP1, MMP3, and MMP9 in the gene profiles of cancer cells." (PMID 38419037, 2024). "The possible molecular mechanism involves inhibiting cleaved CASP3, MMP3, SRC, MAPK10 and CDK6, and activating PPARα and JAK, which are typically involved in cancer pathways, the PI3K-Akt signaling pathway and viral carcinogenesis pathways." (PMID 38675723, 2024). "As for the genes MMP3 and ADH4, which are identified by both indicators as inhibitory factors for cancer onset, they are both in the top 4 positions of both indicators, indicating a strong inhibitory role in the KIRC cancer onset process." (PMID 38459043, 2024). "Among 36 genes, MMP1, HSP90B1, PTK2, MMP3, NOTCH1 and CDH5 had higher methylation status at pan-cancer level." (PMID 38694917, 2024). "Studies have widely reported that KRT4, IGFBP3, MMP10, MMP3, and TGFBI are involved in the pathogenesis of LC and other cancers." (PMID 38302910, 2024).
cancer (continued). "MMP1, MMP3, and MMP10 are highly expressed in HNSCC, compared to other cancers by analyzing the data of Oncomine and GEPIA databases." (PMID 38302910, 2024). "qRT-PCR analysis displayed that the mRNA expression of MMP-2, MMP-3, MMP-7, and MMP-9 in the cervical tissue of patients with cancer was significantly greater than that in the control (p = 0.005, p < 0.001, p < 0.001, and p = 0.038, respectively)." (PMID 39247608, 2024). "We validate the generality of EDS and apply it to effectively block the proteolysis of cell surface receptors in cancer (CDCP1 and EphA2) and the proteolytic activation of three proenzymes in cell migration (MMP1, MMP3, and MMP9)." (PMID 38683990, 2024). "Studies have reported the benefit of retinoids in preventing cancer invasion and metastasis by targeting proteases (MMP-1, MMP-2, MMP3, uPA) involved in the degradation of the extracellular matrix (ECM)." (PMID 38249515, 2023). "Meanwhile, the relative expression level of MMP1, MMP3, and MMP9, related to the proliferation of cancer cells in the downstream pathway was significantly decreased." (PMID 37477531, 2023). "Meanwhile, we noted that Matrix Metalloproteases (MMPs), including MMP1, MMP3, MMP7, MMP10 and MMP13 genes were significantly upregulated in the BSE group, and they were almost universally upregulated in cancer." (PMID 37697300, 2023). "Transcriptome analysis revealed that CHRM3 knockdown significantly reduced an array of classic factors involved in cancer invasive growth, including MMP1/MMP3/MMP10/MMP12 and CXCL1/CXCL5/CXCL8." (PMID 37744266, 2023). "CD147 has been shown to facilitate the secretion of extracellular matrix-degrading metalloproteases from fibroblasts, endometrial cells and cancer cells, such as MMP-1, MMP-3, MMP-9 and membrane type 1-MMP." (PMID 34997863, 2022). "Notably, our data showed that CRC cells secreted TSG-6 could trigger a paracrine activation of JAK2-STAT3 signaling and reprogram normal fibroblasts into cancer-associated fibroblasts, which exhibited upregulation of pro-metastatic cytokines (CCL5 and MMP3) and higher movement ability." (PMID 35280699, 2022). "The pan-cancer survival network further enriches the inhibition of matrix metalloproteases (A2M, MMP1, MMP14, MMP3, TIMP4)." (PMID 35106465, 2022). "Following Cd exposure, the direction of the most differentially expressed genes such as SPP1, MMP3 and SULF1 in fibroid cells favored cellular migration, proliferation and cancer progression as predicted by IPA pathway analysis." (PMID 35453667, 2022). "Several of these specialized TME microenvironments are enriched by the pan-cancer survival network, for example HIF1A signaling (p = 4.27 × 10−6; FGF2, IGF2, MMP1, MMP14, MMP3, PIK3R3, SERPINE1, TGFB1)." (PMID 35106465, 2022). "In the present study, MMP3 staining varied between the canine OSA, including in stromal cells consistent with results in studies of human cancers." (PMID 34414229, 2021). "MMP3 and MMP13 are matrix metalloproteinases which degrade extracellular matrix proteins and can also facilitate cancer cell metastasis to the lungs." (PMID 33777801, 2021). "Overexpression of GPNMB by retrovirus transfection in glioma cells is accompanied by MMP-3 and MMP-9 increase, both increasing metastasis and cancer invasion." (PMID 34054862, 2021). "These cytokines have been identified to be directly or indirectly responsible for cancer progression through remodeling of ECM by upregulating the expression of molecules such as MMP2, MMP3, MMP9, MMP10, MMP13, PLAU, ICAM1 and VCAM1." (PMID 34946170, 2021). "As a result, CXCL10, IGF1, MMP3, MMP1, ICAM1, and IL-13 levels were markedly up-regulated within NPC samples relative to the non-carcinoma samples (P < 0.05)." (PMID 34544905, 2021). "It has been revealed that MMP-3 and MMP-13 mediate the remodeling of ECM and contribute to the metastasis of cancer cells." (PMID 32711573, 2020).
cancer (continued). "For example, MMP2, MMP3, and MMP9 are direct or indirect target genes of FoxO3a in endothelial as well as cancer cells, and FoxO4 upregulated MMP9 expression in smooth muscle cells stimulated by tumor necrosis factor‐α (TNF‐α) by an indirect mechanism." (PMID 32790044, 2020). "Moreover, soluble E-cadherin in serum serves as cancer prognostic marker and the soluble fragment in urine corresponds to the 80 kDa ectodermal fragment of the protein, which can be cleaved by several proteases including plasmin, MMP3, MMP7, ADAM10, and ADAM-15." (PMID 32121033, 2020). "Among the five overlapped genes, vimentin and MMP3, which have been widely recognized as key regulators in promoting cancer invasion and metastasis, drew our great attention to postulate that miR-515-3p may exert its suppressive effect on cancer mobility through its regulation on vimentin and MMP3." (PMID 33243974, 2020). "MMP‐3 and MMP‐13 are proteolytic enzymes involved in the degradation of ECM around invasive cancer cells." (PMID 33040485, 2020). "We have compared protumorigenic phenotypes of rapidly metastatic murine cancer cell line LuM1 with a parental cancer cell line Colon26 (aka CT26) and shown that MMP3 and MMP9 were highly expressed in LuM1 cells." (PMID 32429403, 2020). "A high expression level of MMP3 or CCN2/CTGF mRNA was prognostic and unfavorable in particular types of cancers including head and neck, lung, pancreatic, cervical, stomach, and urothelial cancers." (PMID 32260433, 2020). "The other stromelysins, MMP3 and MMP10, were significantly upregulated in 7 cancer types and 10 cancer types respectively." (PMID 31200666, 2019). "This grouping in cluster 2 features high expression of gene cluster B genes (MMP3, MMP10, MMP13, MMP1, and MMP12) in a pattern that is relatively unique among cancer types." (PMID 31200666, 2019). "Stromelysin-1 (MMP-3) belongs to the MMP family and is induced during development, wound repair, inflammation and cancer." (PMID 31652545, 2019). "Top five up-regulated genes in malignant tumours were COL11A1, SFRP2, LCN2, COL2A1 and H19, while top up-regulated genes in benign tumours were MMP3, MMP1, AREG, PTHLH and SFRP2." (PMID 30517191, 2018). "Among malignant tumours, maximum fold change was observed for COL11A1 gene (Log2 FC = 4.8), while among benign tumours maximum fold change was observed with MMP3 gene (Log2 FC = 6.6)." (PMID 30517191, 2018). "Recent findings indicated that several proteases, including MMP-2, MMP-3, MMP-9, presenilin 1, and CD26, are promoters and mediators of EMT processes in different cancer types." (PMID 30134935, 2018). "Studies have confirmed that many early-stage cancers express elevated levels of MMP-2, MMP-3, and MMP-9." (PMID 29390034, 2018). "In fact, our results demonstrated that, except MMP-7, antcin-H also inhibited other MMP gene expressions, such as MMP-2, MMP-3, and MMP-13, which play critical roles in cancer cell invasion." (PMID 29234409, 2017). "The enzyme activities of MMP2 and 3 in GA cancer tissues were higher than those in normal tissues, and MMP8 enzyme activity was lower than those in normal tissues (MMP2, p=0.028; MMP3, p=0.012; MMP8, p=0.0029." (PMID 29285307, 2017). "SIRT1 in stromal cells promotes cancer growth by producing MMP3, whereas SIRT1 in cancer cells inhibits growth via an intracellular event." (PMID 26992208, 2016). "Overexpression of MMP1, MMP2, MMP3, MMP7, MMP9, and MMP13 correlates with worse outcomes in cancer patients." (PMID 27908290, 2016). "The experiments revealed that the mediators of each aspect of cancer cell behavior are diversified: proliferation was driven by IL-6, migration by CXCL8 and CCL2, invasion by IL-6, MMP-3 and uPA, and EMT by TGF-β1." (PMID 26284488, 2015). "MMP-3 and 9 are tightly correlated with the induction of EMT in cancer cells, the characteristic profile adopted by cancer cells to freely migrate into surrounding tissues." (PMID 25897425, 2015).
cancer (continued). "We have previously shown that MMP-3 treatment of mouse mammary epithelial cells leads to upregulation of the Snail transcription factor, a known key regulator of EMT, as well as cancer progression, invasion and metastasis." (PMID 24811539, 2014). "It is a serine protease that converts plasminogen to plasmin, which directly mediates cancer cell invasion by degrading matrix proteins such as collagen IV, fibronectin, and laminin or indirectly by activating MMP-2, MMP-3, MMP-9, and uPA." (PMID 23878609, 2013). "In human cancer cells, MMP-1, MMP-2, MMP-3, MMP-9, and MMP-13 have been found to be correlated with malignant grade and metastasis." (PMID 24047437, 2013). "We also found that the MMP-3 and MMP-9 that regulate metastasis were down regulated in ASH-WEX and TEG-treated cancer cells; normal cells remained unaffected." (PMID 24130852, 2013). "Matrix metallo peptidases like MMP3 and MMP2 were slightly upregulated in normal and cancer cells respectively." (PMID 22321936, 2012). "Consistent with our findings, it was reported that up-regulation of actin and collagen with simultaneous down-regulation of MMP3 and MMP9 occurs as a measure to prevent the cancer formation in experimentally-treated mice." (PMID 21533263, 2011). "Using Immunohistochemistry, we showed over-expression of MMP3, UBE2C and p16 in cancers compared to normal cervical epithelium and varying grades of dysplasia." (PMID 21338529, 2011). "By inhibiting plasmin, TFPI-2 effectively decreases the activation of MMP-1, MMP-3 and MMP-9 and reduces the invasive potential of several cancer cell lines." (PMID 21062455, 2010). "Gelatin zymography showed bands corresponding in size to MMP-2, MMP-3, MMP-9, and MMP-10 enzymes in each of the 24 cancer cases." (PMID 20920372, 2010). "We observed statistically significant diagnostic power for MMP-3, MMP-7, and MMP-26 for stage I and II EC patients, rather than AUC = 0.5, and CA125 only for stage II cancer patients." (PMID 40332487, 2025). "The significant upregulation of MMP3 and MMP9 genes in VCP-overexpressing hCMEC/D3 cells suggests a potential role for VCP in modulating extracellular matrix dynamics and tissue remodeling processes, crucial for angiogenesis and cancer metastasis." (PMID 39802400, 2025). "This up-regulation might be related to the general tendencies of MMPs in cancer, where MMP1 is significantly and almost universally up-regulated, and MMP3 and MMP12 show significant up-regulation in at least 10 types of cancer." (PMID 39596132, 2024). "STAT5A signaling, CSPG4, MMP-1, MMP-3, MMP-8, MMP-9, and LUM are all involved in cancer cell migration, invasion, and metastasis, while PKM supports the growth and survival of cancer cells by favoring aerobic glycolysis." (PMID 39201614, 2024). "Additionally, it has been shown that MMP-3 can activate other metalloproteinases, such as MMP-1, MMP-7, and MMP-9, mainly to activate cancer cell division." (PMID 38203373, 2023). "In our study, Dex reduced the formation of NETs and the expression of MMP-3 and MMP-9, which might retard the EMT of cancer clinically." (PMID 36910600, 2023). "For cancer cells, cholesterol inhibition during 3D culture increased levels of ECM modification enzyme Mmp3, the integrin Itga2, and inflammation response factors Ptges and Areg; these trends in all genes were consistently reversed when exogenous cholesterol was added." (PMID 37626861, 2023). "Some MMPs, including MMP-3 and MMP-7, are involved in the transport of cancer cells." (PMID 38203373, 2023). "In addition to degrading various ECM components, MMP3 can activate MMP9 and the collagenases, and degrade a number of cell surface molecules, including E-cadherin which contributes to cancer development." (PMID 36677584, 2023). "We can assume that in these circumstances the cancer cells did not limit the MMP-10 secretion to the extracellular space to such a huge extent as MMP-3." (PMID 36231910, 2022).
cancer (continued). "MMP1, MMP3, and MMP12 were up-regulated in both inflammation and cancer." (PMID 35850748, 2022). "Cannabigerol-specific effects included the inhibition of angiopoietin-1, MMP3 and VCAM-1, indicating that its anti-cancer effects may be mediated by the modulation of vascular-immune interactions." (PMID 36923728, 2022). "The increase of several MMPs' expression and enzymatic activity, such as MMP-1, MMP-2, MMP-3, MMP-7, MMP-9, MMP-10, and MMP-14, correlates with the aggressiveness of different types of cancer, which leads to consider them as prognostic markers and targets of new therapeutic strategies." (PMID 36213817, 2022). "In particular, nuclear MMP-3 can regulate connective tissue growth factor (CTGF) expression by interaction with the heterochromatin protein gamma, and CTGF increases the transcription of several MMPs, including MMP-1, -2, -3, and -9, in cancer cells." (PMID 36142454, 2022). "Finally, we confirmed the expression of PTGS2 and MMP3 in various cancer tissues and high expression of PTGS2 and MMP3 in HNSC through Human Protein Atlas (HPA) database." (PMID 36555343, 2022). "In contrast to MMP-2 and MMP-3, high MMP-7 levels were frequently detected in advanced clinical stage NPC patients in this study, suggesting a possible role for MMP-7 in the determination of advanced cancer in NPC." (PMID 34078895, 2021). "Cancer can produce a wide spectrum of proteases, including MMP-1, MMP-3, MMP-7, MMP-8, and MMP-14." (PMID 34769032, 2021). "In vitro studies have also demonstrated the impact of P. gingivalis and F. nucleatum on the upregulation of matrix metalloproteinases, including MMP-2, MMP-3, and MMP-9, which degrade the extracellular matrix and the basement membrane enabling cancer cells to invade and translocate to other sites." (PMID 34299675, 2021). "Nevertheless, of the total number of patients analyzed with cancer, we identified that MMP-1 staining intensity and MMP-3 staining percentage and intensity were significantly increased in the cancerous tissues by 62.3% and 67.5%, respectively, compared to the normal mammary tissues." (PMID 34445715, 2021). "This study reported for the first time that CK2 down-regulation in human cancer cells enhances the expression of SASP factors (IL-1β, IL-6, and MMP3) by NF-κB activation through two pathways: an SIRT1-dependent/AKT-independent pathway and an SIRT1/AKT-dependent pathway." (PMID 33401686, 2021). "MMP3 protein was majorly located in cell membrane or distributed between the cytoplasm, but in the normal nonmalignant tissue or atypical hyperplasia adjacent to cancers, weak or no MMP3 staining was detected." (PMID 32922541, 2020). "To examine whether MMP3 and/or CCN2/CTGF expression are correlated with the prognosis of patients suffering from these types of cancers, we carried out survival analyses using the Kaplan–Meier plot." (PMID 32260433, 2020). "In addition, a list of known JUN-target genes, including MMP3, CD44, EGFR, ENPP246, and MGST147, were markedly upregulated in cancer cells with SH3RF3 overexpression." (PMID 32427938, 2020). "In the current study, we found that MMP3 was abundantly detected in the high-metastatic cancer cells, their non-EV fluids, and EVs, but not in/from MMP3-KO cells." (PMID 32429403, 2020). "A panel of MMPs was analyzed in serum from PC patients—specifically, MMP-1, MMP-3, MMP-7, MMP-9, MMP-10, and MMP-12 were higher in cancer patients compared with healthy donors, showing good diagnostic accuracy, of which MMP-7 and MMP-12 achieved perfect discrimination." (PMID 30678058, 2019). "MMP3, MMP7, MMP12 and MMP14) are significantly up-regulated in at least 10 cancer types." (PMID 31200666, 2019). "Our previous reports also have established that a number of matrix metalloproteinases (MMPs), known to be upregulated in cancers, including OSCC, bind and interact with specific MMPs in biochemical and biologic systems: MMP2 with BSP; MMP3 with OPN; MMP9 with DMP1; and MMP20 with DSPP." (PMID 30002682, 2018).